CLSTN1 (calsyntenin 1)
Diseases named in the same sentence as CLSTN1 in open-access papers (continued):
Sharing a sentence is not in itself a finding about the gene and the disease.
tumor (10 papers, 2017 to 2025). "Expression of CLSTN1 in endothelial cells was positively associated with a higher mTORC1 expressional profile, which was stronger in tumor-associated endothelial cells." (PMID 40198126, 2025). "Although CLSTN1 is most closely associated with vesicle trafficking in neurons, we observed expression in the endothelial cells within tumors, as well as tumor cells and fibroblasts." (PMID 40198126, 2025). "The functions of ESRP1 and CLSTN1 as biomarkers have also been verified in clinical samples, providing the potential for screening individuals at risk of tumor metastasis and early clinical intervention." (PMID 38114495, 2023). "We demonstrate that Raptor-deficient endothelial cells exhibit deficiencies in endosomal trafficking, having reduced expression of calysintenin-1 (Clstn1) involved in anterograde endosomal transport that correlates with an mTORC1 activity gene signature in human tumor–associated endothelial cells." (PMID 40198126, 2025). "These functions of CLSTN1 are in part controlled by MAP4 kinases, as P/12k, a neuroprotective, novel selective inhibitor of this kinase family, increased plasma membrane-associated CLSTN1 expression in MB tumor cells and enhanced CLSTN1 localization in tumor-astrocyte interactions." (PMID 39762313, 2025). "We confirmed CLSTN1 localization to heterotypic tumor-astrocyte interactions using primary mouse cerebellar astrocytes." (PMID 39762313, 2025). "In regions of tumor-iNHA cell interactions, we also detected CLSTN1 accumulations, indicating that CLSTN1 is localized to both homotypic and heterotypic cell interactions." (PMID 39762313, 2025). "We found that CLSTN1 expression is decreased in primary MB tumors compared to tumor-free cerebellum or brain tissues." (PMID 39762313, 2025). "Collectively, these data indicate that co-culture of UW228 tumor cells with iNHAs increased CLSTN1 localization to cell-cell contacts." (PMID 39762313, 2025). "In conclusion, our study provides a first insight into potential tumor-restrictive interactions between tumor cells and astrocytes, which involve CLSTN1 and its regulation by the MAP4 kinase family." (PMID 39762313, 2025). "Taken together, this data indicates a reduced expression of CLSTN1 in MB tumor cells and points towards tight control of CLSTNs during cerebellar development." (PMID 39762313, 2025). "CLSTN1 accumulation was particularly evident in contacts between tumor cells and iNHA after P/12k treatment, where it focally accumulated specifically in contacts between UW228 and iNHA." (PMID 39762313, 2025). "CLSTN1 was expressed in both tumor and healthy epithelial cells, while CYP2R1 had almost undetectable expression." (PMID 41145488, 2025). "Our live-cell imaging analysis of the subcellular dynamics of CLSTN1 confirms anterograde trafficking in MB tumor cells." (PMID 39762313, 2025). "Co-culture of tumor cells with astrocytes increased CLSTN1 localization in cell-cell contacts, which was further enhanced by MAP4K inhibition." (PMID 39762313, 2025). "Using IFA, we next investigated the localization of endogenous CLSTN1 in tumor cells seeded as monocultures or seeded in co-culture with immortalized normal human astrocytes (iNHAs25)." (PMID 39762313, 2025). "Splicing of CLSTN1 (Calsyntenin 1) has previously been recognised as very important in tumour invasiveness." (PMID 35883549, 2022). "Many of the hub AS events, including AS events in KIFB1, SEC31A, CAST and CLSTN1, were up‐regulated in invasive and diffuse GC tissues and were significantly related to extracellular matrix and tumour stromal score." (PMID 32939931, 2020). "Our study revealed a repressive function of CLSTN1 in growth-factor-driven invasiveness in MB, identified MAP4 kinases as repressors of CLSTN1 recruitment to cell-cell contacts, and points towards CLSTN1 implication in the kinase-controlled regulation of tumor-microenvironment interaction." (PMID 39762313, 2025).
tumor (continued). "Thus, the functional significance of CLSTN1 recruitment and accumulation in regions of cell-cell contacts between tumor cells and astrocytes remains to be determined." (PMID 39762313, 2025). "Depletion of CLSTN1 caused some increase in focal connexin 43 (Cx43) staining in regions of cell-cell contact, but did not affect [Ca2+]i fluctuations in the tumor cells." (PMID 39762313, 2025). "We provide evidence that CLSTN1 may exert tumor-suppressive functions by repressing invasiveness and enabling homo- and heterotypic cell-cell interactions." (PMID 39762313, 2025). "Depletion of CLSTN1 increases growth factor-induced invasion, suggesting that the expression levels of CLSTN1 may determine growth factor-driven invasive capabilities of the MB tumor cells." (PMID 39762313, 2025). "We previously observed an increased MAP4K4-dependent invasiveness in SHH MB tumor cells exposed to 1–2 Gy22, suggesting that the irradiation-induced increase in cell invasion observed could in part be mediated by CLSTN1 downregulation via increased MAP4K4 activity." (PMID 39762313, 2025). "To explore expression levels of CLSTN1 in different established human MB tumor cell lines, we probed lysates of three SHH and three Grp3 MB cell lines with anti-CLSTN1 antibodies by immunoblotting (IB)." (PMID 39762313, 2025). "While BODIPY-C16 transport was significantly reduced in Rptor-KO endothelial cells, Clstn1 knockdown did not further alter BODIPY-C16 intensity in tumor cells, suggesting that CLSTN1 functions downstream of mTORC1 to support transendothelial LCFA transport." (PMID 40198126, 2025). "However, since we observed no changes in [Ca2+]i, we do not think that CLSTN1 expression and localization impacts [Ca2+]ipropagation in MB tumor cells under monoculture conditions." (PMID 39762313, 2025).
cancer (5 papers, 2010 to 2024). A tumor composed of atypical neoplastic, often pleomorphic cells that invade other tissues. "Consistent with our findings, two previous studies have shown that the long isoform of CLSTN1 induces mesenchymal transition and invasiveness, suggesting the role of CLSTN1 isoform switching in promoting malignant potential in various cancers." (PMID 38346537, 2024). "We identified Cg19858017 for KIRC, corresponding to the gene CLSTN1, which can be used as a biomarker for a variety of cancers." (PMID 36676027, 2022). "Most of the candidate genes of which we confirmed cancer-specific AS in NSCLC are also involved in these processes (ADD3, CLSTN1, FN1, MYO18A, NUMB, SYNE2, and TPM1)." (PMID 21118496, 2010).
cardiovascular diseases (1 paper, 2024). "Calsyntenin-1(CLSTN1) plays a critical role in the nervous system, but its relevance in cardiovascular diseases is unknown." (PMID 36350487, 2024).
neurodevelopmental disorder (1 paper, 2019). A behavioral and cognitive disorder with onset during the developmental period that involves impaired or aberrant development of intellectual, motor, or social functions. "However, it remains unclear how the transport function of CLSTN1 impacts key molecule, such as ICAM5 that is known to influence dendritic spine maturation, and how CLSTN1 is involved in neurodevelopmental disorders." (PMID 31680833, 2019). "Future work may investigate the reason for aberrant alteration in CLSTN1 in FXS, determine the factors that regulate CLSTN1 to initiate ICAM5 transportation, and provide mechanistic insights into how dysfunctional CLSTN1 signaling pathway contributes to neurodevelopmental disorders." (PMID 31680833, 2019).
CLSTN1 also shares sentences with these, for which no sentence is quoted: fragile X syndrome (2 papers); Anxiety (1); atypical teratoid rhabdoid tumor (1); breast tumors (1); Cognitive impairment (1); depression (1); dermatosparaxis (1); dilated cardiomyopathy (1); ependymoma (1); frontotemporal dementia (1); glioblastoma (1); glioma (1); mastitis (1); medulloblastoma (1); metabolic syndrome (1); neuroblastoma (1); neurological disorders (1); Parkinson disease (1).